ALB (albumin)
Diseases named in the same sentence as ALB in open-access papers (continued):
Sharing a sentence is not in itself a finding about the gene and the disease.
bleeding (6 papers, 2023 to 2025). "The importance of low albumin levels (less than 3 gr/dl) for predicting mortality in acute gastrointestinal bleeding patients has led to incorporating this variable in the AIMS65 score." (PMID 38137765, 2023). "Predictors of hemorrhage include prior variceal bleeding, large spleen size, poor hepatic function (high ALBI, low albumin), and PVTT, suggesting that individualized prophylaxis strategies should integrate both clinical and hemodynamic parameters." (PMID 41228207, 2025).
cerebral small vessel disease (6 papers, 2014 to 2026). Cerebral small vessel disease is the term currently used to pathological processes that affect the brain parenchymal circulation (arterioles, capillaries, and veins). "Current research indicates that the association between the Albumin/Globulin Ratio (A/G ratio) and cerebral small vessel disease (CSVD) remains unclear." (PMID 38259650, 2023). "Ischemic forms of cerebral small vessel disease are caused by blood–brain barrier damage resulting in extravascular plasma proteins, such as fibrinogen and albumin, which disrupt transmembrane ionic gradients and transport pathways and facilitate local inflammation and oligodendrocyte apoptosis." (PMID 37485473, 2022).
Chylothorax (6 papers, 2010 to 2025). The presence of chyle in the thoracic cavity. "In our patient, a large amount of chylothorax remained after early fasting and infusion of albumin and other symptomatic treatments." (PMID 39296890, 2024).
corneal ulcer (6 papers, 2012 to 2021). Area of epithelial tissue loss from corneal surface; associated with inflammatory cells in the cornea and anterior chamber. "Adhesion of P. aeruginosa strain RT-1, a corneal ulcer isolate, was increased when albumin was adsorbed to a lens surface." (PMID 22259220, 2012). "The albumin content of tears also increases in cases of corneal ulceration." (PMID 23308132, 2013).
Cushing syndrome (6 papers, 2022 to 2025). Cushing's syndrome (CS) encompasses a group of hormonal disorders caused by prolonged and high exposure levels to glucocorticoids that can be of either endogenous (adrenal cortex production) or exogenous (iatrogenic) origin. "The earliest explanation was that the increase of urinary albumin in Cushing's syndrome might be the result of abnormal lipid metabolism." (PMID 37773081, 2023).
cystoid macular edema (6 papers, 2015 to 2025). An autosomal dominantly inherited cystoid macular edema manifesting with macular atrophy, strabismus and, sometimes, pericentral retinitis pigmentosa. "Moreover, there have been sporadic reports of cystoid macular edema associated with albumin-bound paclitaxel in recent years." (PMID 39529884, 2024). "We suspected taxane-related cystoid macular edema and terminated nanoparticle albumin-bound paclitaxel, and started topical dorzolamide treatment." (PMID 34284818, 2021). "Cystoid macular edema resolved within 5 weeks after stopping nanoparticle albumin-bound paclitaxel and starting topical dorzolamide treatment confirming the diagnosis of taxane-related cystoid macular edema." (PMID 34284818, 2021).
E. coli infection (6 papers, 2019 to 2025). "We observed that lower albumin levels and longer PD age increased the risk of treatment failure, similar to the results of another study conducted in our center on the treatment outcome of E. coli infection." (PMID 37234246, 2023). "Total protein (TP) and albumin (ALB) levels were also elevated after E. coli infection compared to the control (P > 0.05) but were partially reversed in the TLBEC group." (PMID 33072056, 2020). "There is currently a lack of literature on the relationship between mortality and serum albumin level in patients with E. coli infections." (PMID 31467670, 2019). "Moreover, Bacillus subtilis alleviates the increase in globulin, LPS and MDA, and the decrease in albumin, T-AOC and T-SOD in the serum caused by Escherichia coli infection." (PMID 36290674, 2022).
empyema (6 papers, 2012 to 2025). An accumulation of pus in a body cavity, usually the pleural space. "Patients with empyema had higher absolute neutrophil count, higher levels of C-reactive protein, procalcitonin, and ferritin, and lower serum albumin levels." (PMID 40868554, 2025). "In case of a spontaneous bacterial empyema, an albumin infusion was used by 73% hepatogastroenterologists and 20% pulmonologists (p < 0.001)." (PMID 37697230, 2023).
epileptic seizures (6 papers, 2019 to 2023). "Innate immune reactions affect the integrity of the blood-brain barrier (BBB), which allows peripheral immune cells and albumin to cross the BBB and the oxidative stress induced by epileptic seizures may also affect the activation of circulating white blood cells." (PMID 36895367, 2023).
gastric adenocarcinoma (6 papers, 2020 to 2024). "For unresectable or recurrent advanced gastric adenocarcinoma (AGC), tri-weekly administration of nanoparticle albumin-bound paclitaxel (nab-PTX) at 260 mg/m2 achieved a response rate of 27.8% in a phase II trial in Japan." (PMID 32926227, 2020). "The study analysed the mRNA expression levels of ALB, BCL-2, NFKB1, HIF1A, and IL-6 in 408 stomach adenocarcinoma samples alongside non-tumour gastric tissues." (PMID 39816318, 2024).
gastric ulcer (6 papers, 2020 to 2025). An ulcerated lesion in the mucosal surface of the stomach. "Meanwhile, the low preoperative levels of albumin seem to indicate poor nutritional condition before surgery and after surgery, like the case with gastric ulcer as comorbidity." (PMID 33153465, 2020). "To date, ecabet sodium is the only commercial drug based on abietane-type diterpenoids which is clinically used in the treatment of gastritis and gastric ulcers in Japan since it possesses high affinity to gastric adherent mucosa, epithelial cells, albumin, and fibrinogen in the ulcer region." (PMID 38004467, 2023). "In addition, changes in the saliva FRAS, uric acid, and AOPP levels and serum ratio of AOPP/albumin from horses with gastric ulcers in the glandular mucosa, and in the serum FRAP, CUPRAC, uric acid levels, and the ratio of AOPP/albumin from horses suffering from CIE, were observed." (PMID 35268236, 2022). "Two pivotal targets, heme oxygenase 1 (HMOX1) and albumin (ALB), are believed to assume a significant role in the treatment of gastric ulcers by the construction of “compounds-target-metabolite” networks." (PMID 38259271, 2023). "Our study revealed that the mean concentrations of IL1-F5, CA-VI, serotransferrin and albumin were significantly higher in horses with clinical gastric ulcers compared to No EGUS horses, which is consistent with previous findings in salivary proteomic profiles of horses with induced gastric ulcers." (PMID 40805041, 2025).
gastritis (6 papers, 2017 to 2025). Inflammation of the stomach. "The temporal association with gastrointestinal symptoms, supported by recent real-world endoscopic evidence, suggests that zolbetuximab-induced gastritis and potential protein-losing gastroenteropathy play critical roles in the albumin decline." (PMID 40563646, 2025). "In all gastritis cases, except MiGa, albumin decreases up to 30-fold, while the fibrinogen concentration increases almost 50-fold, leading to the huge difference in the FAR-MS values." (PMID 35566209, 2022). "As their development and validation will take time, gastritis diagnosis based on the fibrinogen to albumin serum ratio may be a quick way forward." (PMID 35566209, 2022). "However, PPG had the benefits of lower incidence of anastomosis leakage, early dumping syndrome, gastritis and bile reflux, and better recovery of total protein, albumin, hemoglobin, and weight." (PMID 32641052, 2020). "In this aspect, it is comprehensible that serum albumin levels might be lower in the severe form of gastritis since it is a well-known negative acute phase reactant." (PMID 37546692, 2023). "Unfortunately, there are not many studies in the literature to determine whether albumin could be a prognostic factor for the progression of gastritis." (PMID 37546692, 2023).
herpes zoster (6 papers, 2016 to 2025). A common dermal and neurologic disorder caused by reactivation of the varicella-zoster virus that has remained dormant within dorsal root ganglia, often for decades, after the patient's initial exposure to the virus in the form of varicella (chickenpox). "When analyzing the data obtained in this population, we found that the risk of all infections but herpes zoster decreased as the albumin level increased." (PMID 27218256, 2016). "Research has indicated that certain inflammatory markers, such as C-reactive protein and albumin, can serve as early diagnostic indicators for predicting the onset of PHN, particularly in patients with acute herpes zoster." (PMID 41142151, 2025).
HIV-1 infection (6 papers, 2006 to 2022). The type species of lentivirus and the etiologic agent of acquired immunodeficiency syndrome (AIDS). "Women with low serum selenium had more advanced immunosuppression, higher plasma viral loads, lower albumin, more frequent symptoms and signs of HIV-1 infection, and were more likely to have an acute phase response compared to women with normal serum selenium." (PMID 16712720, 2006). "HIV-1 infection can cause the production of various natural autoantibodies, including catalytic antibodies hydrolyzing DNA, myelin basic protein, histones, HIV-integrase, HIV-reverse transcriptase, β-casein, serum albumin, and some other natural substrates." (PMID 35335016, 2022). "Our findings suggest that associations between lower serum selenium, lower CD4 count, and higher plasma viral load may be related to the frequent occurrence of low serum albumin and the acute phase response among individuals with more advanced HIV-1 infection." (PMID 16712720, 2006). "The rate of HIV-1 infection of P4P cells was around 50%, as determined by the ratio of HIV-1 DNA and albumin levels, suggesting that any viral superinfection would probably produce dually infected cells." (PMID 17207276, 2007). "The depletion of human hepatocytes and the decline of human ALB levels in vivo could be results of HIV-1 infection of the liver-immune cell milieu and not related to mismatched transplantation of human HSPCs and hepatocytes." (PMID 29361613, 2018).
hypercortisolemia (6 papers, 2020 to 2025). "Recently, patients with the R218P mutant albumin have been found to also exhibit hypercortisolemia because the same mutation also increases the binding affinity of albumin to cortisol." (PMID 39372822, 2024).
Hypovitaminosis (6 papers, 2010 to 2025). "Besides decreased albumin, important mineral and/or vitamin deficiencies after weaning were the reasons for restarting IVS in patients with ≤60 cm of SB." (PMID 36678209, 2023). "They identified albumin, spring admission and SAPS II score as predictors of hypovitaminosis but levels of 1α,25(OH)2D3 were not estimated." (PMID 21110839, 2010).
idiopathic nephrotic syndrome (6 papers, 2021 to 2025). Nephrotic syndrome for which no cause has been identified. "Our previous study demonstrated that serum albumin level was associated with the incidence of AKI in idiopathic nephrotic syndrome." (PMID 38914959, 2024). "Reviewing the published pediatric population studies, only one study based on the cohort of children with idiopathic nephrotic syndrome included ALB in the final model." (PMID 36313303, 2022). "In addition, Porphyromonadaceae and Enterobacteriaceae were positively correlated with albumin in a study of the gut microbiota of people with idiopathic nephrotic syndrome." (PMID 34946032, 2021).
Intraventricular hemorrhage (6 papers, 2017 to 2025). Bleeding into the ventricles of the brain. "After adjustment for WFNS grade, albumin, Fisher score, symptomatic cerebral vasospasm, age, intraventricular hemorrhage, and DCI, the CRP/albumin ratio was also an independent risk factor for poor outcome of aSAH." (PMID 31781024, 2019). "Moreover, elevated CRP/albumin ratio was significantly associated with unfavorable 3-month outcome, even after adjustment for several factors, including WFNS grade, serum glucose, albumin, Fisher score, age, symptomatic cerebral vasospasm, intraventricular hemorrhage, and DCI." (PMID 31781024, 2019). "After adjustment for WFNS grade, serum glucose, albumin, Fisher score, age, symptomatic cerebral vasospasm, intraventricular hemorrhage, and DCI, the binary logistic regression identified CRP/albumin ratio to be independently related to poor outcomes in patients with aSAH." (PMID 31781024, 2019). "Poor outcome at 3 months was associated with a higher WFNS grade, higher serum glucose, higher CRP level, lower albumin level, higher Fisher score, higher CRP/albumin ratio, symptomatic cerebral vasospasm, intraventricular hemorrhage, delayed cerebral ischemia, and age using univariate analysis." (PMID 31781024, 2019).
kidney cancer (6 papers, 2018 to 2024). Primary or metastatic malignant neoplasm involving the kidney. "In patients after curative resection of kidney cancer, this retrospective study revealed that an early post-operative serum albumin level < 32 g/L is an independent risk factor associated with a decreased RFS and decreased OS." (PMID 30522461, 2018). "Slight decline in albumin level as well as reduced creatinine level and alanine aminotransferase activity were observed in the group of patients with kidney cancer." (PMID 39896931, 2024). "One of the most severe complications of kidney cancer, accompanied with its treatment, is impairment of kidney function, followed by abnormal estimated glomerular filtration rate (eGFR) and urinary albumin‐to‐creatinine ratio (UACR) values." (PMID 36069056, 2023). "In this retrospective study we report for the first time that an early post-operative serum albumin level is another long-term prognostic factor after radical resection of kidney cancer." (PMID 30522461, 2018). "Based on good category power (AUC = 0.71–0.8), an early post-operative serum albumin level deserves more attention in predicting prognosis after radical resection of kidney cancer, especially combined with other prognostic factors." (PMID 30522461, 2018). "Thus, blood biochemistry test is recommended for suspected kidney cancer, with special attention paid to albumin blood level, the erythrocyte sedimentation rate, lactate dehydrogenase (LDH) and alkaline phosphatase activities, as well as blood levels of ionized and total calcium." (PMID 39896931, 2024). "We found that albumin, ALP, BUN, chloride, creatinine, direct bilirubin, eGFR, pH, potassium, total protein, nitrite, strip WBC, and urine occult blood were significantly different in patients with kidney cancer compared to patients with cystitis." (PMID 35054370, 2022). "However, it seems that in kidney cancer, there is no modification of the albumin structure by oxidative stress, which changes the ion-binding sites." (PMID 37568812, 2023). "In addition, whether or not transfusion of albumin leads to decreased tumor recurrence and death after resection of kidney cancer should be investigated." (PMID 30522461, 2018).
lipid metabolism disorders (6 papers, 2013 to 2025). "The decrease in proteinuria is associated with beneficial effects on serum albumin levels and lipid metabolism disorders." (PMID 36613485, 2022). "The decrease in proteinuria positively influenced albumin levels and lipid metabolism disorders." (PMID 36613485, 2022). "However, it is not known whether improving lipid metabolism disorder is associated with ameliorating elevated fetuin-A level or reversing increased urine albumin excretion." (PMID 23710462, 2013).
morbid obesity (6 papers, 2019 to 2025). An excess of body weight, normally defined as an individual with a body mass index greater than 35 or a body weight greater than one hundred percent of ideal body weight. "In addition, another study carried out in Germany, in patients with morbid obesity, found that 88% had low serum albumin results (<40 g/dL), describing an association between morbid obesity and a low consumption of essential micronutrients." (PMID 35010957, 2021).
necrotizing fasciitis (6 papers, 2011 to 2026). "In the present study, we determined the association between in-hospital mortality and serum albumin levels at presentation to the emergency department (ED) among patients with necrotizing fasciitis." (PMID 30423847, 2018). "However, literature about the diagnostic performance of serum albumin levels among patients with necrotizing fasciitis is limited." (PMID 30423847, 2018). "Among widely used laboratory markers, band polymorphonuclear neutrophils >10%, serum creatinine level >2 mg/dL, hyperlactatemia, laboratory risk indicator of necrotizing fasciitis (LRINEC) score >8, and serum albumin levels have been identified in association with mortality." (PMID 30423847, 2018).
Oral ulcer (6 papers, 2014 to 2026). Erosion of the mucous mebrane of the mouth with local excavation of the surface, resulting from the sloughing of inflammatory necrotic tissue. "Logistic regression analysis showed that rash (p = 0.036), oral ulcer (p = 0.027), high 24 h UTP (p < 0.001), high creatinine (p = 0.017), and low serum albumin (p = 0.003) were significantly associated with poor early prognosis in childhood‐onset LN." (PMID 39935233, 2025). "Logistic univariate analysis found that oral ulcers, increased 24 h UTP, and decreased albumin were all risk factors for poor prognosis." (PMID 39935233, 2025). "This included 1 case of stomach flatulence in the XXK group and 6 cases in the CDS group, including heart burn, abnormal liver function, positive urinary albumin, and oral ulcer." (PMID 25394847, 2014). "In summary, if LN child have rash, oral ulcers, high level of 24 h UTP and serum creatinine, low level of serum albumin, it may indicate a poor prognosis." (PMID 39935233, 2025).
osteomyelitis (6 papers, 2021 to 2025). An acute or chronic inflammation of the bone and its structures due to infection with pyogenic bacteria. "One study ofindividuals with DFU and osteomyelitis found that ESR, WBC count, CRP level, and theCRP/albumin ratio were significantly elevated, whereas the albumin level wasdrastically decreased in patients with osteomyelitis compared to those withoutosteomyelitis." (PMID 40622101, 2025). "Increased albumin levels could be due to dehydration and chronic infection/inflammation, e.g., osteomyelitis and endocarditis." (PMID 35528506, 2022).
overnutrition (6 papers, 2016 to 2024). An imbalanced nutritional status resulting from excessive intake of nutrients. "MHD recipients with DM experience overnutrition as evidenced by higher BMI, FTI, and energy intake, with a paradoxically higher predisposition to PEW as expressed by a higher SGA score and lower serum markers of nutrition, e.g., albumin, total cholesterol, and creatinine." (PMID 35057428, 2022).
peripheral sensory neuropathy (6 papers, 2015 to 2025). "Notably, this study demonstrated a significant association between albumin-bound paclitaxel and peripheral neuropathy, with a reporting odds ratio (ROR) for peripheral sensory neuropathy as high as 37.01 (95% CI: 24.271–56.43)." (PMID 39529884, 2024).